INS (insulin)
Diseases named in the same sentence as INS in open-access papers (continued):
Sharing a sentence is not in itself a finding about the gene and the disease.
Insulin resistance (continued). "The problem of the insulin-resistance in women with pre-pregnancy obesity is that their already overburdened pancreatic beta cells face an additional strain during pregnancy to increase insulin secretion to meet the demands of the fetus." (PMID 37861742, 2024). "Chronic consumption of such HFD has been associated with increased metabolic diseases, including an imbalance in the insulin-glucose signaling axis, leading to insulin resistance." (PMID 39095788, 2024). "One of the major hallmarks of insulin resistance is impaired signal transduction in the insulin/PI3K/Akt signaling pathway, leading to an increase in GSK-3β." (PMID 38683825, 2024). "Due to interference with insulin signaling, high levels of oxidative stress in adipocytes contribute to insulin resistance." (PMID 38892574, 2024). "The OGTT insulin AUC increases with insulin resistance due to both the increased need for insulin to compensate for impaired insulin action and reduced insulin clearance mainly by the liver." (PMID 38201980, 2024). "Upon exercise, myostatin decreases, and its expression has been correlated to a decrease in plasma levels of glucose, insulin, and IL-6 and a reduction in IR (calculated with the Homeostatic Model Assessment for Insulin Resistance Index, HOMA-IR)." (PMID 39337980, 2024). "Mice with β cell–specific Sucnr1 deficiency exhibited impaired glucose tolerance and insulin secretion on a high-fat diet, indicating that SUCNR1 is essential for preserving insulin secretion in diet-induced insulin resistance." (PMID 38713514, 2024). "Fetuin-A knockout mice were found to have impaired insulin resistance, as indicated by increased glucose clearance, enhanced insulin sensitivity, and reduced serum FFAs and TGs." (PMID 39139641, 2024). "T2DM is a complex metabolic disorder characterized by insulin resistance (IR), which reduces the body’s sensitivity to insulin, resulting in dysregulated blood glucose control." (PMID 39514584, 2024). "These factors not only diminish insulin responsiveness in muscle but also exacerbate insulin resistance." (PMID 39334887, 2024). "During pregnancy, the measurable changes in circulating SCFA composition, increased FFAR2 expression, enhanced FFAR2 signaling, increased insulin secretion, and β cell proliferation compensate for pregnancy-related insulin resistance in together." (PMID 38248846, 2024). "The whole-blood Se concentration, fasting plasma insulin and glucose, glycohemoglobin (HbA1c), and homeostatic model assessment for insulin resistance (HOMA-IR) were measured." (PMID 37880477, 2024). "These dAGE products are shown to increase insulin resistance, while a restricted intake of dietary glycoxidation products improved insulin sensitivity in diabetic mice." (PMID 38257161, 2024). "Numerous studies have reported that many alkaloids, including palmatine, columbamine, and coptisine, possess properties such as reducing blood sugar, promoting insulin secretion, improving insulin resistance, and enhancing glucose utilization." (PMID 38792165, 2024). "As the TyG index is indicative of insulin resistance, our findings support a role for insulin in promoting PCa progression." (PMID 38087039, 2024). "It improved glycemic control by reducing fasting blood glycosylated hemoglobin, serum insulin, and insulin resistance, as well as homocysteinemia in patients with type 2 diabetes." (PMID 38612580, 2024). "It has been shown that cinnamon extract reduces blood glucose levels and improves insulin resistance in rats by increasing insulin activity and glucose metabolism in fat cells." (PMID 38195613, 2024). "The pathophysiology of type 2 diabetes involves the development of insulin resistance, wherein target cells exhibit reduced responsiveness to insulin." (PMID 38548784, 2024). "This persistent inflammation further impairs insulin signaling, worsening insulin resistance and promoting hyperglycemia and other metabolic abnormalities." (PMID 39596980, 2024).
Insulin resistance (continued). "In the early stage of insulin resistance, energy surplus leads to β cell super-secretion of insulin in response to the excessive glucose, which acts through mitochondrial production of excess ATP in the cells under mitochondrial overheating." (PMID 39873003, 2024). "As long as pancreatic β-cells are able to compensate for insulin resistance by enhancing insulin secretion and increasing β-cell mass, euglycemia can be maintained." (PMID 38533089, 2024). "Insulin resistance in obesity is characterized by impaired insulin signaling pathways, particularly in adipose and hepatic tissue." (PMID 39000518, 2024). "Gal‐3 levels correlate with insulin, glucose, insulin resistance, and dyslipidemia in women with polycystic ovary syndrome." (PMID 39230472, 2024). "Insulin resistance leads to increased insulin and blood glucose levels, reducing glucose uptake and increasing peripheral tissue decomposition." (PMID 39834471, 2024). "Activation of glucagon receptor leads to insulin resistance in the liver, fat, and muscle for induction of gluconeogenesis and lipolysis in a way against insulin activity." (PMID 39873003, 2024). "Insulin / insulin resistance, aromatase / aromatase inhibitors, gonadotropin, inositol and even vitamin D were appearing on both HA PCOS and NA PCOS causes." (PMID 38347589, 2024). "AN frequently occurs in conjunction with insulin resistance, and interestingly, the RIPE drug isoniazid has been implicated in insulin derangements in patients, most notably diabetics." (PMID 39165464, 2024). "In the future, to accurately evaluate insulin resistance and insulin sensitivity, the number of participants studied should be increased and the intervention timing should be unified." (PMID 39803116, 2024). "Inflammatory cytokines such as tumor necrosis factor-α and interleukin-6 interfere with insulin signaling pathways, further exacerbating insulin resistance and impairing glucose uptake by cells." (PMID 39765947, 2024). "Among those 32 papers, glucose, insulin, and insulin resistance (HOMA-IR) were most commonly measured and reported." (PMID 39519417, 2024). "Insulin resistance, which frequently occurs in obesity, promotes fat accumulation in liver cells by enhancing fat breakdown and elevating insulin levels." (PMID 39458511, 2024). "Visceral fat releases adipokines that impair insulin sensitivity, and an imbalance between Omega-6 and Omega-3 fatty acids creates a pro-inflammatory environment, further contributing to insulin resistance." (PMID 39796335, 2024). "Metformin’s ability to improve insulin sensitivity and reduce hyperglycemia is particularly relevant in HBV-infected individuals, as insulin resistance is associated with worse outcomes in chronic liver disease." (PMID 39772244, 2024). "Altogether, including our work, this suggests that UA-induced insulin resistance is heavily mediated through inflammatory pathways that disrupt insulin signaling, corroborating previous findings on the link between inflammation and insulin resistance." (PMID 39728460, 2024). "Metformin is an insulin sensitizer that is widely used for the treatment of insulin resistance in polycystic ovary syndrome patients." (PMID 38637876, 2024). "The hepatic insulin resistance and decreased hepatic insulin clearance both contribute to hyperinsulinemia and thus to the development of peripheral tissue insulin resistance in the skeletal muscles." (PMID 39769002, 2024). "Impaired insulin sensitivity, also known as insulin resistance (IR), contributes to the pathophysiology of diabetes and serves as a crucial element contributing to ASCVD." (PMID 38898520, 2024). "Research has extensively documented insulin resistance compounded by defective insulin secretion in obese individuals with T2DM, yet the pathophysiology in non-obese individuals is not as well understood due to the focus predominantly on obese populations." (PMID 39588337, 2024).
Insulin resistance (continued). "Insulin resistance (IR) is a metabolic disease characterized by impaired response of target tissues to insulin, leading to abnormal glucose and lipid metabolism." (PMID 39054513, 2024). "Insulin resistance leads to elevated insulin levels, resulting in increased secretion of insulin-like growth factor-1 (IGF-1), decreased production of sex hormone-binding globulin (SHBG), and increased levels of free sex hormones." (PMID 39469573, 2024). "This is frequently related to poor glycemic control, elevated insulin dosage needs, and insulin resistance." (PMID 39768947, 2024). "The study of insulin resistance in Iraqi women with IH revealed some degree of insulin resistance and increased basal serum insulin levels." (PMID 39925819, 2024). "Insulin resistance (IR), which arises from disruptions in any of these processes and the failure of target cells to adequately respond to insulin, involves both intracellular and extracellular signaling disturbances." (PMID 39770980, 2024). "The pancreatic β-cells’ ability to secrete insulin is reduced by hyperglycemia in the toxicity cycle, which is then followed by a rise in insulin resistance, which worsens hyperglycemia and renders β -cells completely ineffective." (PMID 38371502, 2024). "The secretion of this protein is positively regulated in response to oxidative stress and is related to insulin resistance and the alteration of insulin signaling in AD, being a critical regulator of memory consolidation." (PMID 39768255, 2024). "Second, insulin resistance is the body’s weakened response to endogenous or exogenous insulin, which is related to the disorder of lipid metabolism." (PMID 38491412, 2024). "Considering that the HOMA-IR is a calculation used to evaluate the degree of insulin resistance when there is high insulin resistance, we have peaks in insulin production in the attempt to maintain blood glucose levels within normal limits." (PMID 38892604, 2024). "Insulin resistance in skeletal muscle impairs the ability of insulin to regulate glucose homeostasis, leading to glucose intolerance and hyperglycaemia." (PMID 39095777, 2024). "Generally, insulin resistance in non‐obese subjects can be identified using glucose tolerance tests and measurements of insulin, lipids, blood pressure, BMI and waist circumference." (PMID 37938877, 2024). "A metabolic score for insulin resistance (METS-IR) combines non-insulin fasting laboratory values and anthropometric measurements to assess insulin resistance and is valuable for evaluating cardiac metabolic risk." (PMID 39598197, 2024). "It is calculated on the basis of fasting insulin and glucose levels and interpreted in the following manner: if the score is >1, it is considered abnormal; if the score is >2, it indicates insulin resistance." (PMID 38792339, 2024). "Insulin resistance can induce significant alterations in the compensatory responses of insulin secretion, resulting in decreased glucose tolerance." (PMID 38921462, 2024). "As chronic metabolic disease is tightly related with glucose tolerance and insulin resistance, we further tested fasting blood glucose and insulin levels." (PMID 38338579, 2024). "During insulin resistance, the liver’s response to insulin is reduced, leading to increased hepatic glucose production (gluconeogenesis) and further exacerbating hyperglycemia." (PMID 39683601, 2024). "Their excessive production can contribute to insulin resistance and impaired insulin secretion, creating a detrimental cycle." (PMID 39435991, 2024). "The present study demonstrates that stress increases insulin secretion in chickens but also induces insulin resistance." (PMID 38473137, 2024). "Studies have shown that dysfunctional insulin signalling can worsen pathology related to Alzheimer’s disease, suggesting insulin resistance is a link between metabolic syndrome and neurodegenerative disorders." (PMID 38177108, 2024).
Insulin resistance (continued). "In the UK, South Asian children exhibit greater insulin resistance than white European children, with girls showing more insulin resistance than boys, indicating both sex and ethnic differences in insulin sensitivity and body composition." (PMID 39125938, 2024). "Generally, evidence agrees that fenretinide reduces expression of retinol-binding protein 4 an adipokine thought to contribute to insulin resistance, and as a result, improved insulin sensitivity." (PMID 39408263, 2024). "In relation to secondary outcome measurements, an improvement in lipid profile, liver enzyme tests, FBG, insulin concentration, and insulin resistance is expected." (PMID 39039602, 2024). "Moreover, our data with the previous finding that compensatory β-cell proliferation in mice requires glycolysis and membrane depolarization suggest that insulin secreted by glucose may act in an autocrine manner to promote β-cell growth when hyperglycemia is caused by HFD-induced insulin resistance." (PMID 38201998, 2024). "Insulin resistance is a condition where the body’s cells become less responsive to insulin, leading to elevated blood sugar levels and disrupted glucose and lipid metabolism." (PMID 38998642, 2024). "This is in line with previously published literature assessing the effect of elevated BMI, an indicator for high insulin resistance and low insulin sensitivity, in relatives of individuals with type 1 diabetes." (PMID 37914981, 2024). "One study described a case of a 21-year-old patient initially thought to have T1DM who required high dose of insulin, which raised the suspicion for insulin resistance, especially with presence of acanthosis nigricans." (PMID 39108603, 2024). "A direct connection can be made between BA signaling and T2DM by FOXO1, a gluconeogenic transcription factor that should be inhibited by insulin signaling, but in insulin resistance paradoxically remains active." (PMID 38664391, 2024). "During the acute phase, inadequate insulin secretion in the presence of insulin resistance likely contributes to the development of hyperglycemia." (PMID 37934800, 2024). "Higher doses of retatrutide reduced biomarkers of insulin resistance, including fasting insulin, fasting C-peptide and HOMA2-IR, by up to 50% or more from baseline." (PMID 38858523, 2024). "Some studies have shown a negative correlation between SFRP4 expression and insulin secretion, and plasma levels of SFRP4 have been positively correlated with insulin resistance and negatively correlated with insulin capacity to suppress lipolysis." (PMID 38834984, 2024). "Some essential metabolic adaptations of pregnancy are an increase in insulin resistance, an accelerated hepatic glucose production, as well as a surge in insulin release from pancreatic beta cells, to allow for an increased delivery of nutrients to the fetus." (PMID 37861742, 2024). "Protein-restricted FGR rats showed insulin resistance and altered insulin signaling in skeletal muscles after 12 weeks." (PMID 39430205, 2024). "Increased fasting blood sugar (FBS), fasting insulin (FI), and insulin resistance (HOMA-IR) are observed in patients with NAFLD." (PMID 38729941, 2024). "To assess the impact of an HCD on insulin resistance, we measured fasting glucose and fasting insulin levels in both WT and db/db mice." (PMID 39200168, 2024). "From a physiopathological perspective, GDM is characterized by β-cell dysfunction (impaired insulin secretion) and insulin resistance (decreased insulin-stimulated glucose uptake in skeletal muscle and adipose tissue), like T2DM." (PMID 39064123, 2024). "Here, we summarize the latest development of optogenetics and its integration with synthetic biology approaches to produce light‐responsive cells for insulin/GLP‐1 production, amelioration of insulin resistance and neuromodulation of insulin secretion." (PMID 38751366, 2024).
Insulin resistance (continued). "Reaven further proposed that hyperinsulinemia/insulin resistance to insulin-stimulated glucose uptake plays a pivotal role in the pathogenesis and clinical course of three major related diseases: type 2 diabetes, hypertension, and CAD." (PMID 39769002, 2024). "Biological mechanisms leading to cellular insulin resistance include disruptions in insulin signaling pathways, such as the blockage of phosphorylation of insulin receptors and insulin receptor substrates, along with dysfunction in the PI3K and AKT pathways." (PMID 39280009, 2024). "High blood TG levels are a marker of insulin resistance, as insulin normally promotes the uptake of TG from the blood." (PMID 39596499, 2024). "Insulin resistance (IR) in PCOS is caused by impaired insulin action characterized by compensatory hyperinsulinemia (HI) and reduced insulin response to glucose overload." (PMID 38255975, 2024). "Adipocytes play a crucial role in glucose uptake and insulin response, which contributes to the progression towards insulin resistance." (PMID 39749015, 2024). "These inflammatory changes inhibit insulin signaling, activate gluconeogenic enzymes, and exacerbate hepatic insulin resistance." (PMID 39409124, 2024). "Estrogens activate the ERα pathway in insulin-sensitive tissues, conferring protection against insulin resistance." (PMID 39484344, 2024). "Significant positive associations were found for 11KT, A4, and T with insulin and HOMA-IR, indicating the relation of these androgens to insulin resistance." (PMID 39273637, 2024). "Just as HOMA-IR is a surrogate marker of insulin resistance, insulin requirements can to some extent express the degree of insulin resistance." (PMID 38601785, 2024). "Excessive levels of insulin in the blood as a result of insulin resistance are referred to as hyperinsulinemia." (PMID 39410536, 2024). "Glycemic indices (insulin resistance, insulin sensitivity, and β cell function) were calculated using the homeostasis model." (PMID 39055387, 2024). "The decrease in insulin secretion, coupled with the progression of insulin resistance, can lead to the development of T2D." (PMID 39458933, 2024). "This indicates that targeting treatments related to the low-level phosphorylation of FOXO1 in insulin resistance can improve insulin sensitivity." (PMID 39021599, 2024). "Obesity leads to an increase in insulin resistance, and in this case, body cells respond less to insulin." (PMID 39188978, 2024). "Betaine supplementation reduced whole body insulin resistance and increased activation of insulin signaling pathways in the liver in a mouse model of insulin resistance and fatty liver created by feeding a nutritionally complete high fat diet for 14 weeks." (PMID 39119463, 2024). "This was likely due to increased fasting insulin levels after HFSD in both female groups, indicating compensatory increased insulin secretion in response to energy-rich HFSD-induced insulin resistance." (PMID 39545055, 2024). "In the animal model, CME and FCME significantly reduced body weight, plasma insulin levels, insulin resistance, and accumulation of fat compared to the obese control group." (PMID 39598313, 2024). "ITTs were subsequently conducted to evaluate systemic insulin sensitivity, and our finding showed a marked insulin resistance following 24 weeks of HFD treatment." (PMID 38557554, 2024). "Insulin resistance can directly affect endometrial function by altering insulin signaling pathways in uterine tissue." (PMID 39767708, 2024). "Among the several molecules that can impair insulin signal transduction in hepatocytes, cytokines have been shown to increase in diabetic patients and induce insulin resistance." (PMID 38892230, 2024). "Chronic inflammation is an essential factor leading to PI3K/AKT insulin signaling pathway damage, which is a primary trigger of insulin resistance (IR)." (PMID 38254507, 2024).